LINC01449 (long independently transcribed non-coding RNA 1449)
Gene: Long non-coding RNA gene on chromosome 7 (41,089,539 to 41,133,507, forward strand). Ensembl gene ENSG00000224017.
Diseases named in the same sentence as LINC01449 in open-access papers:
LINC01449 is named in the same sentence as 2 diseases in open-access papers, as found by Europe PMC text mining. Sharing a sentence is not in itself a finding about the gene and the disease.
LINC01449 shares sentences with these, for which no sentence is quoted: fibroids (2 papers); tumor (1).